PLPBP (pyridoxal phosphate binding protein)
Description:
Pyridoxal 5'-phosphate (PLP)-binding protein, which may be involved in intracellular homeostatic regulation of pyridoxal 5'-phosphate (PLP), the active form of vitamin B6.
Synonyms: PROSC; EPEO1; EPVB6D
Tractability: PROTAC: ubiquitination databases record sites on it.
Gene: Protein-coding gene on chromosome 8 (37,762,585 to 37,779,770, forward strand). Ensembl gene ENSG00000147471.
Subcellular location (Human Protein Atlas): Cytosol
Gene Ontology:
Molecular function: pyridoxal phosphate binding
Biological process: vitamin B6 metabolic process
Cellular component: cytosol; mitochondrion; cytoplasm
Genetic constraint (gnomAD): Loss-of-function variants: 21 observed, 28.83 expected, observed/expected ratio (o/e) 0.73, 90% interval 0.52 to 1.05. The upper end of that interval is the gene's LOEUF score, 1.05, which puts it in group 4 of 6, group 1 being the genes least tolerant of losing a copy. Missense variants: 305 observed, 351.9 expected, observed/expected ratio (o/e) 0.87, 90% interval 0.79 to 0.95. Synonymous variants: 124 observed, 133.85 expected, observed/expected ratio (o/e) 0.93, 90% interval 0.8 to 1.08.
Homologues: Orthologues: chimpanzee PLPBP (99% identical), dog PLPBP (90% identical), pig PLPBP (88% identical), mouse Plpbp (87% identical), guinea pig PLPBP (84% identical), rat Plpbp (84% identical), tropical clawed frog plpbp (69% identical), zebrafish plpbp (66% identical), Drosophila melanogaster CG1983 (45% identical), Caenorhabditis elegans F09E5.7 (16% identical).
Diseases named in the same sentence as PLPBP in open-access papers:
PLPBP is named in the same sentence as 20 diseases in open-access papers, as found by Europe PMC text mining. Sharing a sentence is not in itself a finding about the gene and the disease. The quoted sentences say what the papers report.
epilepsy (10 papers, 2017 to 2024). A brain disorder characterized by episodes of abnormally increased neuronal discharge resulting in transient episodes of sensory or motor neurological dysfunction, or psychic dysfunction. "Recently, biallelic variants in PLPBP coding for pyridoxal 5′-phosphate homeostasis protein (PLPHP) were identified as a novel cause of early-onset vitamin B6–dependent epilepsy." (PMID 37451483, 2023). "PLPBP deficiency, however, is another B6‐dependent epilepsy associated with low‐CSF‐PLP akin to PNPO deficiency." (PMID 32888189, 2021). "It is important to differentiate between PNPO deficiency and other B6‐dependent epilepsies, including alpha‐aminoadipic semialdehyde dehydrogenase (ALDH7A1) deficiency and pyridoxal phosphate‐binding protein (PLPBP) deficiency." (PMID 32888189, 2021). "Hence, diagnosis of different B6‐dependent epilepsies is best established by the identification of biallelic pathogenic variants in the ALDH7A1, PNPO and PLPBP genes." (PMID 32888189, 2021). "Therefore, mutations in the PLPBP gene disrupt this process, causing PLP to react with other substrates and impacting the metabolism of important amine or amino acid neurotransmitters in the brain, consequently leading to the development of epilepsy." (PMID 40217438, 2024).
pyridoxine-dependent epilepsy (5 papers, 2021 to 2024). A rare neurometabolic disease characterized by recurrent intractable seizures in the prenatal, neonatal and postnatal period that are resistant to anti-epileptic drugs (AEDs) but that are responsive to pharmacological dosages of pyridoxine (vitamin B6). "The non-specificity of metabolic biomarkers may even be misleading (e.g., patients with pyridoxine-dependent epilepsy due to PLPBP gene mutations were misdiagnosed with mitochondrial or glycine encephalopathies due to non-specific abnormalities in metabolic testing)." (PMID 35328062, 2022).
Encephalopathy (2 papers, 2018 to 2021). Encephalopathy is a term that means brain disease, damage, or malfunction. "In fact, the current protocol should be regularly updated in order to accommodate newly discovery IEMs, such as uridine-responsive encephalopathy due to biallelic CAD mutations and vitamin B6-responsive epileptic encephalopathy due to biallelic PLPBP mutations." (PMID 30559706, 2018).
Epileptic spasm (2 papers, 2022 to 2023). A sudden flexion, extension, or mixed extension-flexion of predominantly proximal and truncal muscles that is usually more sustained than a myoclonic movement but not as sustained as a tonic seizure. "Epileptic spasms were also recently reported without an associated hypsarrhythmia in a 5-month-old infant presenting with combined paroxysmal eye-movement disorders and carrying a previously unreported bi-allelic pathogenic PLPBP variant." (PMID 36980111, 2023).
Brain atrophy (1 paper, 2022). Partial or complete wasting (loss) of brain tissue that was once present. "In the PDE and PLPBP deficiency groups, seizures were controlled by pyridoxine monotherapy, and the remaining one had refractory seizures due to secondary brain atrophy." (PMID 35495162, 2022).
hypophosphatasia (1 paper, 2023). Hypophosphatasia (HPP) is a rare heritable metabolic disorder characterized by defective mineralization of bone and/or teeth in the presence of reduced activity of unfractionated serum alkaline phosphatase (ALP). "The mean age at seizure onset was 59.8 ± 291.6 days (data available for 429/497 patients), with earlier onset in hypophosphatasia and PLPBP deficiency." (PMID 36980111, 2023).
infantile spasms (1 paper, 2022). A rare epilepsy syndrome characterized by onset of epileptic spasms in infants between 2 and 12 months of age, and rarely up to 24 months. "In the etiologies of infantile spasms, especially genetic etiology, PDE, PNPO deficiency, and PLPBP deficiency account for only a rare proportion." (PMID 35495162, 2022).
PNPO deficiency (1 paper, 2023). "Of these, 90.7% (431/497) were diagnosed with the following three disorders: ALDH deficiency (69.4%), PNPO deficiency (13.2%), and PLPBP deficiency (9.2%)." (PMID 36980111, 2023).
PLPBP also shares sentences with these, for which no sentence is quoted: breast carcinoma (3 papers); dependent (2); Hypsarrhythmia (2); tumor (2); cancer (1); Epileptic encephalopathy (1); glycine encephalopathies (1); lung carcinoma (1); Mitochondrial encephalopathy (1); Neonatal seizure (1); Ohtahara syndrome (1); protein deficiency (1).